IL17A (interleukin 17A)
Diseases named in the same sentence as IL17A in open-access papers (continued):
Sharing a sentence is not in itself a finding about the gene and the disease.
colitis (continued). "In the current study, AVCP administration significantly reduced the elevated serum levels of IL-1β, IL-6, TNF-α, and IL-17A induced by DSS in mice, which suggests that AVCP can reduce inflammation in colitis mice." (PMID 40507195, 2025). "This metabolic shift enhanced IL-17A and IL-22 production by ILC3s, thereby strengthening the intestinal barrier and relieving the disease in a DSS-induced colitis model." (PMID 40498001, 2025). "In this study, we investigated the mechanisms by which TH17 cells and their cytokines (IL-17A and IL-22) control local inflammation and render resistance to DSS-induced colitis and CRC development." (PMID 40749055, 2025). "Genetic ablation of Nrp1 resulted in reduced ILC3 frequency and IL-17A production, thereby ameliorating DSS-induced colitis." (PMID 40498001, 2025). "We found that TH17 cells and their IL-17A and IL-22 render resistance to DSS-induced colitis and CRC development through blocking immune cell infiltration into the local epithelial tissues, which is associated with chemokine expression in epithelial tissues." (PMID 40749055, 2025). "Genetic deficiency of NRP1 reduces the frequency of intestinal ILC3s and impairs their ability to synthesize IL-17A, with the downstream effect of altering the composition of the microbiota and attenuating DSS-induced colitis." (PMID 41194916, 2025). "KO of either C/EBPβ or STAT3 in colon epithelial cells abolished the protective functions of IL-17A and IL-22 against DSS-induced colitis." (PMID 40749055, 2025). "Th17 cytokines, such as IL-17A, IL-17F, IL-21, and IL-22, have a dual effect on IBD, attenuating or increasing effects in the gut, as shown in experimental colitis models." (PMID 40565877, 2025). "IL-17A production and Th17 cell accumulation were significantly lower in the colons of Gpr15−/− mice than in those of Gpr15+/+ mice with TNBS-induced colitis." (PMID 40957881, 2025). "In Il10−/− Il17a−/− mice, the high concentration of MDSC-expressed NO induced the barrier disruption of gut microbiota and exacerbated the pathology of the colitis." (PMID 37733169, 2024). "Our findings suggest that LCN2 specifically regulated ILC3s, particularly the NKp46+ILC3 subgroup, to secrete IL-22 and IL-17A by targeting GPX4, thereby exerting a protective effect on colitis." (PMID 39300068, 2024). "Because TH1 and TH17 contribute to pathogenesis of colitis driven by naïve CD4+ T lymphocytes, we sought to clarify the roles for cytokines IFN-γ and IL-17A in lymphopenia-induced immune responses of MP cells." (PMID 39630890, 2024). "The results demonstrated that SP decreased mRNA levels of IL-6, TNF-α, IL-17A, and IL-1β, but enhanced the mRNA level of IL-10 in mice with DSS-induced colitis." (PMID 38725846, 2024). "However, it is controversial whether IL-17A inhibitors increase the risk of developing colitis in patients who do not have underlying IBD." (PMID 38060157, 2024). "Collectively, intestinal colonization with C. tropicalis enhanced IL-17A/IL-22 expression, barrier function, and epithelial cell proliferation in the colon of mice with DSS-induced colitis." (PMID 39462273, 2024). "Accordingly, in a rodent model of disease, CD30L−/− mice appear resistant to chemical colitis due to impaired expression of multiple cytokines including IFN-γ, IL-17A, and IL-10." (PMID 38903247, 2024). "Accordingly, IL-17A and IL-17R knockout mice are resistant to dextran sulfate sodium (DSS)- and 2,4,6-trinitrobenzene sulfonic acid-induced colitis, respectively." (PMID 37239894, 2023). "We identified polyfunctional mucosal CD4+ and CD8+ T cells that co-produce IFNγ, other pro-inflammatory cytokines (e.g. IL22, IL17A) and cytotoxic molecules, including granzyme B, as key effector cells in CPI colitis." (PMID 37872166, 2023). "The results showed that neutralization of IL-17A, IL-17F, or both substantially alleviated the DSS-induced colitis development in wild-type mice, with more obvious effect when simultaneously blocking both." (PMID 36792629, 2023).
colitis (continued). "TCRβ-/- mice transferred with CD4-Cu2++DSF T cells had lower IL-17A and IL-17F mRNA levels in DSS-induced colitis than those transferred with CD4 control." (PMID 37284442, 2023). "Consistent with more severe colitis in neutrophil-depleted mice, higher proportions of IFN-γ-, IL-17A- and TNF-α-expressing TCRγδ+CD8αα+ IELs were detected in these mice compared to WT controls." (PMID 36729914, 2023). "These CD90- and CD90low ILC are a significant source of IFNγ, IL-13 and IL-17A upon dysbiosis and dextran sulphate sodium (DSS)-elicited colitis." (PMID 37114052, 2023). "Our results showed that vmab-mIL22 had potent synergistic anti-inflammatory and repair-promoting activities through blocking the IL17A pathway and activating the IL22 pathway in an influenza and colitis model." (PMID 37189778, 2023). "For example, it can negatively regulate the expression of intestinal epithelial costimulatory molecules, resulting in the suppression of IL-17A response and dextran sulfate sodium (DSS)-induced colitis." (PMID 35651499, 2022). "EV were shown to suppress induced p65 translocation in a mice colitis model, effectively reducing the release of proinflammatory cytokines TNF-α, IL-6, and IL-17A, and attenuating clinical symptoms of colitis." (PMID 35335634, 2022). "In the present study, the levels of IL-6, IL-17A, IL-1β, and TNF-α were increased, accompanied by increased expression of TLR5/MyD88/NF-κB pathway in TNBS induced colitis rats." (PMID 35571126, 2022). "For example, feeding berberine inhibits IFN-γ and IL-17A in SCID mice administered with CD4+CD45RB high T cells, reduces lamina propria lymphocyte infiltration, and improves colitis." (PMID 36145301, 2022). "The severity of IBD peaked at 6 days after colitis induction, ndSTAT1-TMD, ndSTAT1-TMD (V426D, T427D), or anti-IL-17A antibody treatment was initiated on day 6 through intraperitoneal injection." (PMID 36591260, 2022). "According to one study, in a mouse model of IL-10 gene-deficient colitis, H. hepaticus induced inflammatory Th17, increased IL-17A and IFN-γ expression, and aided in the development of colitis." (PMID 36590401, 2022). "FMT significantly alleviated DSS-induced colitis and decreased immune cell infiltration in colon tissue, and inflammatory factors expression of IL-1β, TNF-α and IL-17a." (PMID 36578000, 2022). "Cells were isolated during colitis, stimulated ex vivo with phorbol 12-myristate 13-acetate/ionomycin, then surface stained for CD3/CD4, fixed, stained for intracellular IL-17A and IFNγ and analyzed by FCM." (PMID 34983695, 2022). "The overall disease activity index (DAI) score of colitis substantially decreased in the ndSTAT1-TMD-treated group, comparable to that of the anti-IL-17A antibody-treated group." (PMID 36591260, 2022). "Nanovesicles isolated from broccoli, called BDNs, decreased TNF‐α, interleukin 17A (IL‐17A) and interferon γ (IFN‐γ) in colonic tissues of mice affected by colitis and showed protective properties by acting on dendritic cells." (PMID 35789531, 2022). "IL-17a demonstrates a higher level in the group of mice fed a HFD and colitis compared to the group only fed a HFD and it is significantly lower in the group with IAP compared to the group HFD + TNBS." (PMID 35328382, 2022). "Among IL-17A+ CD4+ T cells, CD69−CD103− CD4+ T cells accounted for 22.4% in control mice and 33.2% in DSS-induced colitis." (PMID 35844584, 2022). "M2 macrophage-derived exosomes upregulated Treg cells and IL-4, reduced the production of the proinflammatory cytokines IL-1β, IL-6 and IL-17A, reduced the severity of DSS-induced colitis in mice, and played a protective role in colitis." (PMID 36045437, 2022). "In contrast, CD69+CD103+ CD4+ TRM cells only accounted for 2.2% of IFNγ- and 5.1% of IL-17A–expressing CD4+ T cells in control mice, 6.5% of IFNγ- and 3.9% of IL-17A–expressing CD4+ T cells in DSS-induced colitis, respectively." (PMID 35844584, 2022).
colitis (continued). "Broccoli-derived nanovesicles (BDNs) were able to contrast the increase of pro-inflammatory cytokines, such as TNF-α, IL-17A, and IFN-γ, in colonic tissues of two colitis models (DSS-induced and T cell transfer model of colitis)." (PMID 34065193, 2021). "Others showed, using the exact same RORC inhibitor, that while IL-17A levels were reduced, the production of IL-22 continued and treatment with the RORC inhibitor abrogated experimental colitis." (PMID 34552583, 2021). "Several pro-inflammatory cytokines, e.g., TNFα, IL-1β, IL-6, and IL-17A, are known to be involved in DSS-induced colitis." (PMID 33871822, 2021). "The levels of proinflammatory cytokines, including TNF-α, IL-6, interferon-γ (IFN-γ), interleukin-18 (IL-18) and interleukin-17a (IL-17a), were significantly increased in DSS-induced colitis mice (P < 0.05 vs. CON)." (PMID 34675239, 2021). "By using a short-term immunization approach over 6 days, we identified more IL-17A and IFN-γ coproducing Th17 cells, while in a long-term T-cell-driven colitis model over 7 weeks we observed more Th1/exTh17 cells in the absence of Tec." (PMID 35003062, 2021). "At the same time, IL-6, IL-17A, IL-23, TNF-α, and TGF-β1 expressions were significantly decreased in colitis mice treated by SSP." (PMID 32581849, 2020). "First, we found that the colonic mRNA expression levels of the proinflammatory mediators IL-1β, IFN-γ, IL-17A, and TNF-α, which had been confirmed to be involved in IBD, were upregulated notably in colitis mice compared to levels in normal controls." (PMID 32855978, 2020). "In a DSS-induced colitis model, CD4CreTTPf/f mice displayed severe colitis and had more TH17 cells and serum IL-17A compared with wild-type mice." (PMID 32922402, 2020). "The results indicated that SSP inhibited pro-inflammatory factors (as IL-6, IL-17A, IL-23, and TNF-α) and improved IL-10 expression, or restrained TGF-β1 in the colonic tissue of colitis mice." (PMID 32581849, 2020). "Il-17A, a marker for both proinflammatory Th17 cells and innate lymphoid cell (ILC) group 3, plays an important role in the development of Hh-induced colitis in 129SvEv Rag−/− mice." (PMID 33255175, 2020). "As pro-inflammatory factors, IL-6, IL-17A, IL-23, and TNF-α are classical hallmarks of colitis, which induce the occurrence of colitis." (PMID 32581849, 2020). "The discovery of distinct functions of IL-17A and IL-17F produced by TH17 cells highlights a central role for this cell population in regulating adaptive immunity during colitis." (PMID 32391010, 2020). "We have identified distinct roles of IL-17A and IL-17F in modulating DSS-induced colitis in mice and we demonstrated the benefit of quercetin in colitis dependent on Arg-1 secreted by MDSC after ESR/STAT3 activation." (PMID 32391010, 2020). "In conclusion, we have demonstrated distinct roles of IL-17A and IL-17F in DSS-induced colitis mice model which was dependent on increased Arg-1 secreted by MDSC after ESR/STAT3 activation." (PMID 32391010, 2020). "Pretreatment of colitis mice with L. reuteri I5007 significantly reduced the DSS-induced production of TNF-α, IL-6, IFN-γ, and IL-17A, as well as increased the level of IL-10 compared with the DSS group." (PMID 32751784, 2020). "Although both IL-17A and IL-17F are produced by TH17 cells, we found lower expression of IL-17A, and significantly increased expression of IL-17F in ArgmyeKO mice during colitis." (PMID 32391010, 2020). "IL-17A upregulation in the colorectum reportedly facilitated mucosal repair and gut epithelial integrity in a DSS-induced colitis model." (PMID 32391010, 2020). "Of the numerous pro-inflammatory cytokines subsequently produced, the most prominent cytokine is the Th17 cytokine IL-17A, which is critical for ETBF colitis-promoted tumorigenesis." (PMID 33126615, 2020).
colitis (continued). "It has been noted that the reduction in inflammatory cytokines, such as TNF-α, IL-6, IL-1β, IFN-γ, and IL-17A, in the serum represents a target for IBD therapy, as they play leading roles in the formation of colitis." (PMID 32751784, 2020). "Importantly, intestinal NIK signaling is active in mouse models of colitis and patients with inflammatory bowel diseases; meanwhile, constitutive NIK signaling increases the susceptibility to inflammatory injury by inducing ectopic M-cell differentiation and a chronic increase of IL-17A." (PMID 30737385, 2019). "To gain insight into the effect of MMI-0100 on the DSS-induced colitis, we assessed a series of pro-inflammatory cytokines at mRNA levels, such as TNF-α, IL-6, IL-1β, TGF-β, IFN-γ, IL-17A, COX-2 and iNOS." (PMID 31382637, 2019). "In contrast to the effect of AICAR on colitis LP CD4+ T cells, the addition of C.C. increased the frequency of IFN-γ-producing colitis LP CD4+ T cells as well as that of IL-17A-producing LP CD4+ T cells." (PMID 31417110, 2019). "Intracellular cytokine staining of colonic CD3ε+ T cell subsets demonstrated a significant increase in the frequency and absolute cell count of both IL-17A+ γδ and αβ CD4+ T cell subsets in the recovery phase of aDSS colitis." (PMID 30876876, 2019). "Thirdly, the ROC curve analysis showed that a combination of CCL20 and IL-17A was an effective panel for discriminating CRC cases from HD, and colitis from colorectal adenoma cases." (PMID 31387598, 2019). "In this colitis model, a large amount of the Th1-related cytokine IFN-γ and a small amount of the Th17-related cytokine IL-17A are known to be secreted by LP CD4+ T cells." (PMID 31417110, 2019). "Recently, it has been reported that Th17 cells, which mainly produce IL-17A, are also involved in the progression of DSS-induced colitis." (PMID 29888292, 2018). "Levels of proinflammatory cytokines, such as TNF, IFN-γ, IL-6, IL-12, IL-17A, and IL-23 were elevated in the serum of DSS-induced colitis mice." (PMID 29892282, 2018). "Recently, it has been reported that a novel subset of helper CD4+ T cells producing IL-17A, namely, Th17 cells, was involved in the progression of DSS-induced colitis." (PMID 29888292, 2018). "First we confirmed our results by showing that IL-17A (Th17) and IFNγ (Th1) are decreased in MLN from LL-pILMAM group in DNBS-induced colitis." (PMID 28203226, 2017). "IL-9-producing type I NKT cells protect against DSS-induced colitis through IFN-γ and IL-17A suppression, as well as IL-10 and TGF-β upregulation, depending on IL-4 production by type I NKT cells." (PMID 28095507, 2017). "Very interestingly, we found that both the transcript and protein expression level of IL-17A and Act-1 were enhanced after LFS-01 treatment compared to DSS-induced colitis group." (PMID 29375374, 2017). "To confirm the Th1/17 responses in CS exposure-induced colitis, we analyzed the intracellular expression of IFN-γ and IL-17A on CD4+ T cells in MLNs and colonic LP." (PMID 29163466, 2017). "During the development of colitis or CAC, we observed a significantly reduced secretion of IL-17A in the colon of lmp7−/− and rag1−/−lmp7−/− mice as compared to WT and rag1−/− control animals, respectively." (PMID 28881574, 2017). "DSS-induced colitis is mediated by Th1 and Th17 responses, resulting in increased numbers of IFN-γ- and IL-17A-producing CD4 T cells in the inflamed colonic tissue." (PMID 27058552, 2016). "In line with this, we found that Th17 (CD4+IL-17A+) and Th2 (CD4+IL-4+ and CD4+ IL-5+) obviously decreased in IL-21RKO mice with DSS-induced colitis." (PMID 27545302, 2016). "Compared to the control, Th1 cell populations (CD4+IFNγ+) and Th17 subsets (CD4+IL-17A+) increased in the spleen, MLN and colon tissues of mice with colitis as well as the enhanced concentrations of IFNγ and IL-17 in colon homogenate supernatants." (PMID 26728323, 2016).
colitis (continued). "Colitis induced by WT T cells is characterized by a multifunctional response with high amounts of IFN-γ and GM-CSF and a lower IL-17A and IL-22 response." (PMID 27193261, 2016). "The fact that the elevated inflammatory cytokine expression such as IFNγ and IL-17A in the colon and accumulation of CD4+ T cells in cLP were observed in LTAC mice raised the question of whether these T cells turned out to gain pathogenic characters that would contribute to onset of colitis." (PMID 26132627, 2015). "Immunologically, experimental colitis was characterized by proinflammatory responses with upregulation of colonic IFN-γ and IL-17A levels, thus resembling the immune profile of Crohn’s disease." (PMID 25313594, 2014). "To further demonstrate that CECs were a critical target of IL-17A-mediated negative regulation in vivo, we transferred CECs or co-transferred CECs and IL-17A into TNBS colitis mice." (PMID 24586980, 2014). "The levels of TNF-α and IFN-γ increased, but IL-6, IL-17A and IL-4 decreased in lamina propria (LP) of colon in immune milk-fed mice with DSS-induced colitis." (PMID 24686517, 2014). "On the other hand, as above specified, IL-17A and IFN-γ from NKp46-negative ILCs3 contribute to sustain inflammation in innate IBD models, such as anti-CD40 or H. hepaticus-induced colitis." (PMID 25061260, 2014). "Severe colitis was mediated by increased local expression of cytokines (IL-6, IL-10, TNF-α, IFN-γ and IL-17A) and phosphorylation of Leucine-rich repeat kinase 2 (LRRK2)." (PMID 24873968, 2014). "In detail, real-time PCR data from colonic tissues showed very high expression levels of proinflammatory IL-17A and IFN-γ mRNA in the colon of colitis mice, as well as an increase in colonic IL-4 and IL-10 mRNA, albeit to a lesser extent." (PMID 25313594, 2014). "Intestinal inflammation in the adoptive transfer colitis model examined by ELISA was also characterized by higher concentrations of IFN-γ, IL-17A and IL-10 in the colon supernatants compared with CONTROL mice." (PMID 25313594, 2014). "Rag KO recipients of CD8+ T cells from VDR KO mice had more IFN-γ and IL-17A in the SI and colon that corresponded to the increased severity of naïve CD4+ T cell induced colitis." (PMID 24502291, 2014). "We produced unique double deletions of mice that were either IL-17A−/−IL-2Rα−/− or IFN-γ−/−IL-2Rα−/− to specifically address the precise role of these two cytokines in the natural history of autoimmune cholangitis and colitis." (PMID 25133396, 2014). "In murine colitis models, IL-17A production from CD4+ T cells is protective because IL-17A directly suppresses the development of colitogenic Th1 cells via IL-17R expressed on activated CD4+ T cells." (PMID 23383714, 2013). "In our study, DSS-treated B6 C3ar-/- mice had lower IL-17A and IFN-γ levels than B6 WT, indicating that C3aR participates in the regulation of T cell-mediated responses in DSS-induced colitis." (PMID 23638016, 2013). "Mice with colitis infected with H. polygyrus had higher concentrations of IL-6, IL-12p70, IL-10, IL-22 and MCP-1 but lower amounts of IL-17A (from 5.4 pg/mL to 3.2 pg/mL) at 6 DPI." (PMID 24167594, 2013). "However, recent studies suggested that IL-12p40 homodimer may have higher affinity for the IL-23 receptor than IL-12 receptor, and IL-12p40 delivery ameliorated dextran sulfate sodium-induced colitis by suppressing IL-17A production and inflammation in the intestinal mucosa." (PMID 24382939, 2013). "In the dextran-sodium-sulfate- (DSS-) induced colitis model, in which disease progression is primarily due to increased neutrophilic infiltration of the inflamed tissue, mice lacking IL-17F or IL-17A or mice treated with an anti-IL-17A antibody show severe weight loss and colonic epithelial damage." (PMID 22229105, 2012). "Surprisingly, our data show that pretreatment with La-IFN-β exacerbates DSS colitis, with an increase in TNF-α, IFN-γ, IL-17A and IL-13 production by intestinal tissues over the controls." (PMID 21365015, 2011).